RIBC1 (RIB43A domain with coiled-coils 1)
Synonyms: FLJ32783; 2610028I09Rik
Tractability: Small molecule: a structure with a bound ligand is known.
Gene: Protein-coding gene on chromosome X (53,421,951 to 53,431,624, forward strand). Ensembl gene ENSG00000158423.
Subcellular location: Cytoplasm, cytoskeleton, flagellum axoneme
Subcellular location (Human Protein Atlas): Nuclear bodies
Gene Ontology:
Molecular function: protein binding
Biological process: flagellated sperm motility
Cellular component: axonemal A tubule inner sheath; sperm flagellum
Homologues: Orthologues: chimpanzee RIBC1 (99% identical), macaque RIBC1 (96% identical), dog RIBC1 (73% identical), pig RIBC1 (73% identical), rat Ribc1 (67% identical), mouse Ribc1 (66% identical), tropical clawed frog ribc1 (42% identical), zebrafish ribc1 (34% identical), Drosophila melanogaster CG7264 (26% identical). Paralogues in human: RIBC2 (35% identical).